U6 (U6 spliceosomal RNA )
Synonyms: LOC124903413
Gene: Small nuclear RNA gene on chromosome 14 (24,352,057 to 24,352,157, reverse strand). Ensembl gene ENSG00000283290.
Gene Ontology:
Molecular function: U4 snRNA binding
Biological process: formation of quadruple SL/U4/U5/U6 snRNP; spliceosomal tri-snRNP complex assembly
Cellular component: U4/U6 x U5 tri-snRNP complex; U6 snRNP
Homologues: Orthologues: chimpanzee U6 (100% identical), macaque U6 (95% identical), mouse Gm25332 (75% identical), pig U6 (75% identical), rat LOC120099431 (73% identical). Paralogues in human: RNU6-1316P (90% identical), RNU6-214P (90% identical), RNU6-1031P (89% identical), RNU6-20P (89% identical), RNU6-21P (89% identical), RNU6-35P (89% identical), RNU6-1145P (88% identical), RNU6-128P (88% identical), RNU6-19P (88% identical), RNU6-211P (88% identical), RNU6-25P (88% identical), RNU6-310P (88% identical), and 1286 more.